IRAK1 (interleukin 1 receptor associated kinase 1)
Diseases named in the same sentence as IRAK1 in open-access papers (continued):
Sharing a sentence is not in itself a finding about the gene and the disease.
tumor (continued). "IRAK1 facilitates this process through the promotion of adhesion molecule (VCAM-1 and ICAM-1) expression, which enables tumor cells to adhere to the endothelium." (PMID 39451208, 2024). "The mRNA expression of six inflammation-related genes (C3, CTNNB1, CYBC1, DNASE1L3, IRAK1, and SERPINE1) is closely related to the overall survival rate, tumor immune infiltration, and clinical stage of HCC patients." (PMID 39055701, 2024). "It regulates inflammation and the immune response by targeting pro-inflammatory cytokines and molecules like IRAK1 and TRAF6, reducing inflammation and potentially affecting the tumor microenvironment." (PMID 39061157, 2024). "On the other hand, both IRAK1 and RIOK1 were downregulated and involved in tumor initiation, tumor progression, poor outcome, and radiotherapy resistance." (PMID 36845147, 2023). "IRAK1 and IRAK4 were significantly higher expressed in LGG samples than non-tumor tissues from the Rembrandt database." (PMID 35211171, 2022). "Lower levels of SIGIRR and of TOLLIP, NFRKB, TNFRSF1A, and CD14 and of two distinct MAP kinases were detected in all the cancer cell lines analyzed; on the contrary, IRAK1 and HSPD1 mRNAs were upregulated in all the tumor cells." (PMID 35814450, 2022). "In that study, we found that miR-490-3p acted as a tumor-suppressive miRNA in CRC cells, and expression of its gene targets (IRAK1, FUT1, and GPRIN2) was significantly predictive of 5-year overall survival in CRC patients." (PMID 36232922, 2022). "It appears from our fairly detailed survey of cytokines and chemokines that IFN-γ is one of the effectors for tumor cell immune evasion in SCLL, which is regulated by IRAK1 signaling." (PMID 34906138, 2021). "IRAK1 expression frequency increased in HCC progression, correlates with tumor size and metastasis; IRAK1 upregulation significantly predicts poor survival." (PMID 30279971, 2018). "IRAK1 knockdown or inhibition reduced TNBC cell invasion, mammosphere formation; IRAK1 shRNA inhibits tumor growth in a TNBC mouse model; paclitaxel-treated TNBC cells acquire resistance that can be overcome by IRAK1/4 inhibitor + paclitaxel." (PMID 30279971, 2018). "Tumor suppressor STK4 levels inversely correlate with IRAK1 in HCC macrophages; IRAK1/4 inhibitor I had anti-tumor effects in STK KO HCC mice." (PMID 30279971, 2018). "Primary AML cells have high IRAK1 mRNA levels; IRAK 1 and/or 4 inhibition is antiproliferative; IRAK1/4 inhibitor reduces tumor burden and prolongs survival when combined with Bcl-2 inhibitor or vinblastine." (PMID 30279971, 2018). "Suppression of IRAK1, by either siRNAs or the pharmaceutical IRAK1/4 inhibitor, lessened cell proliferation in HCC cell lines in vitro and HCC xenograft tumor growth in vivo." (PMID 27619757, 2016). "Suppression of IRAK1 by small interference RNA (siRNA) or a pharmaceutical IRAK1/4 inhibitor impeded cell growth, induced apoptosis and lessened HCC xenograft tumor growth." (PMID 27619757, 2016). "In vivo analyses also validated that FOXP3-mediated induction of miR-146a resulted in the downregulation of IRAK1 and TRAF6 and subsequently inhibited NF-κB activation, thus leading to tumor suppression in breast cancer cells." (PMID 26682271, 2015). "Indeed, adding back the supernatant of control MB436 sphere cells to the IRAK1-depleted MB436 cells restored the sphere-forming capacity and suggested that IRAK1-regulated cytokine production might be crucial to TNBC tumour growth through induction of the CSC subpopulation." (PMID 26503059, 2015). "Ultimately, FOXP3-induced miR-146a/b inhibited NF-κB activation by repressing IRAK1 and TRAF6, which led to tumor suppression and apoptosis during tumor initiation in breast and prostate epithelial cells." (PMID 26682271, 2015). "We confirm it modulates differentiation and expression of important tumor-promoting signaling pathways in macrophages, such as NFκB, STAT3, Notch 3 and IRAK1." (PMID 25599228, 2015).
tumor (continued). "In these same cells, IRAK1 knockdown combined with TRAF6 knockdown by siRNA increased invasion and tumor volume, but IRAK1 knockdown alone had few effects." (PMID 26527316, 2015). "The molecular mechanisms through which miR-146a contributes to tumor development are unclear but they seem to be related to the ability of this miRNA to target some mRNAs, such as TRAF6, IRAK1, CXCR4, NF-κB and EGFR." (PMID 24376808, 2013). "IRAK1 was overexpressed in HCC tumor tissues and may play a carcinogenic effect in HCC through the TLR-IRAK pathways." (PMID 40665355, 2025). "Using in vitro and in vivo studies, they demonstrated that high levels of IRAK1 in HCC enhance the expression of AKR1B10, a downstream effector of AP-1 and a main regulator of tumor-initiating cells (TICs), thereby promoting doxorubicin or sorafenib resistance." (PMID 39451208, 2024). "Significantly, the scaffolding function of IRAK1 and not its kinase activity is essential for tumor cell survival in this context." (PMID 38792088, 2024). "The analysis showed that normal breast, colon, cerebral cortex, and ovary tissues exhibited a negative or weak staining of IRAK1, while in the corresponding tumor tissues, such expressions displayed moderate or strong staining." (PMID 35669566, 2022). "In addition, the expression level of IRAK1 was positively correlated with tumor stage in ACC, KICH, KIRP, and KIRC, suggesting that IRAK1 plays an important role in predicting tumor malignancy and aggressiveness." (PMID 35669566, 2022). "Our data further suggested that the combination can inhibit IRAK1/NF-κB and ERK signaling pathways, resulted in down-regulation of inflammatory factors and S100A7/9 expression, which are the main cytokines in tumor microenvironment contributed to CSC phenotype and function." (PMID 32547883, 2020). "(i) IRAK1 and PIN1 are both sufficient to force R-RT in otherwise radiosensitive tumor cells." (PMID 31799178, 2019). "To confirm whether the results of cell culture reflected in vivo conditions, we measured TLR5, IRAK-1, and IRAK-4 gene expression in tumor tissue induced by MKN45cl85 and 85As2 cells." (PMID 30410674, 2018). "Furthermore, HCMV deubiquitinase acquires pro-tumor functions by inhibiting PRR-mediated type I interferon via deubiquitination of TRAF6, TRAF3, IRAK1, IRF7 and STING." (PMID 28981114, 2017). "These in vitro effects were also seen in vivo as MB436, but not MDA231 xenograft tumours bearing IRAK1 shRNA exhibited significant growth inhibition in Dox-treated non-obese diabetic/severe combined immunodeficiency (NOD/SCID) mice for 21 days." (PMID 26503059, 2015). "MiR-146a has a growing list of presumed targets including, TRAF6, IRAK1, CXCR4, NF-κB, which may contribute to inflammation and tumor development." (PMID 25490205, 2014). "Within these proteins, we considered IRAK1 and CSF1R as potential pharmacological targets for the treatment of LUAD, based on previous research indicating they could be targeted by FDA-approved drugs, though in other tumor types." (PMID 38182978, 2024). "Our screening results indicated that IRAK1 depletion may result in radiation resistance, suggesting that multiple mechanisms link the IL-1/IL1R pathway with radiation response and the outcomes may vary depending on tumor context." (PMID 38316463, 2024). "Several of the genes targeted by miR-28 in B cells, including Bcl-2, NF-κB2 and IRAK1, have been shown to be essential for oncogenic signaling in the ABC and GCB genetic subtypes of DLBCL, and our findings are thus in agreement with the anti-tumor effect of miR-28 observed in ABC- and GCB-DLBCL." (PMID 37852959, 2023).
tumor (continued). "We, therefore, investigated whether targeting other members of the IL-1 pathway (Caspase-1, IL1β or IRAK1) could reduce bone metastases without increasing tumour growth outside of the bone." (PMID 36230739, 2022). "Besides, IRAK1 correlated positively with pathology stages and tumor grades (for grades there was a slight trend without statistical significance)." (PMID 36421353, 2022). "Unlike other inhibitors of the IL-1 pathway, inhibition of IRAK1 with Pacritinib had very little effect on bone metastasis, reducing metastatic outgrowth of disseminated tumour cells in the bone by 12% compared with control, 18 days post tumour injection." (PMID 36230739, 2022). "Chromosome 1q21.3, encoding IRAK1, is amplified in recurrent BC; S100A7/8/9 and IRAK1 drive tumorsphere growth, disrupted by pacritinib via IRAK1, not JAK2; pacritinib TGI in xenograft models via IRAK1; pacritinib + paclitaxel caused durable tumor regressions in a neoadjuvant TNBC model." (PMID 30279971, 2018). "As another example, an evaluation of over 300 tumor samples from non-squamous cell lung cancer (NSCLC) patients showed that tumor tissue had significantly increased cytosolic IRAK-1 expression and decreased nuclear expression relative to adjacent normal tissue." (PMID 25452754, 2014). "Although it seems likely that other factors in addition to miR-146a may be involved in the down-regulation of IRAK1 and TRAF6 during the progression of OSCC, the effects of miR-146a expression in modulating IRAK1 down-regulation can be shown in advanced tumor samples." (PMID 24302991, 2013). "As a result, tumor volume and weight were found to be reduced in the presence of HDAC4 or IRAK1 knockdown either under or not under irradiation, while the reduction was more substantial in the presence of irradiation (8 Gy)." (PMID 35193602, 2022). "Similarly, Dox-induced IRAK1 knockdown impaired both the primary and secondary mammosphere formation in IRAK1 high-expressing TNBC cell lines, but not MDA231 cells, indicating a role of IRAK1 in both tumour-initiating and self-renewal capacity." (PMID 26503059, 2015). "For miR-146a, NF-κB dampening through IRAK1/TRAF6 targeting can reduce inflammatory cytokines and support anti-tumor immunity, yet in specific inflammatory milieus negative-feedback regulation may also favor tumor persistence by blunting acute immune activation." (PMID 41226828, 2025).
cancer (70 papers, 2012 to 2025). A tumor composed of atypical neoplastic, often pleomorphic cells that invade other tissues. "Interleukin receptor‐associated kinase 1 (IRAK1) reportedly plays an important role in a series of malignant tumors and is overexpressed in HCC tissues and cell lines." (PMID 39778021, 2025). "In cancer cells, IRAK1 is frequently activated, and the activation is linked to the progression and therapeutic resistance of various types of cancers." (PMID 39451208, 2024). "While IRAK1 has been implicated in a variety of cellular processes beyond cancer, this review is specifically focused on its role in cancer metastasis and its associated mechanisms." (PMID 39451208, 2024). "IRAK1 has been implicated in promoting various aspects of these invasive phenotypes across several cancer types." (PMID 39451208, 2024). "Through prime editing, we characterized three variants in cancer-relevant genes (MFN2, FOSL2, and IRAK1), demonstrating their cancer-driving potential." (PMID 38637555, 2024). "S100A8/9 and CXCL1/2, or S100A7/8/9 and IRAK1, form a feedback loop to cause cancer chemoresistance and drive breast cancer tumor sphere growth." (PMID 32547883, 2020). "Triple-negative breast cancer often shows overexpression of interleukin-1 receptor-associated kinase 1 (IRAK1), and paclitaxel treatment activates IRAK1, which increases the stemness of cancer cells and confers resistance to paclitaxel treatment." (PMID 32046099, 2020). "IL-1β release by lingual squamous cell carcinomas causes upregulation of the IL-1R and increased levels of p-IRAK-1 in cancer associated fibroblasts." (PMID 25452754, 2014). "Moreover, IRAK1 activation is frequently associated with progression and therapeutic resistance of cancers." (PMID 41395111, 2025). "The miR-146b-5p/IRAK (Interleukin-1 receptor-associated kinase 1) interaction also suppresses NF-κB, inhibiting the production of IL-6 (interleukin-6) and IL-8 (interleukin-8), which contribute to osimertinib resistance in this type of cancer." (PMID 40283927, 2025). "IRAK1 expression was associated with poorer prognosis in different cancer types." (PMID 35669566, 2022). "IRAK1 is associated with inflammatory diseases and several types of cancers." (PMID 36421353, 2022). "The function of the miR-146b-IRAK1 axis may be potentially associated with EMT by regulation of E-cadherin in PTC cancer cell lines." (PMID 28294980, 2017). "Pacritinib is an IRAK1 inhibitor used to upregulate PD-L1 expression and inhibit the proliferation of cancer cell lines." (PMID 40804837, 2025). "Additional evidence highlighting the significance of IRAK-1 in cancer comes from studies focusing on microRNAs (miRNAs)." (PMID 41011273, 2025). "IRAK1 is a kinase involved in inflammation and innate immune response, as well as in cancer progression." (PMID 40804837, 2025). "IRAK1 is a downstream effector for TLR signaling pathways, with inflammatory, autoimmune, and cancer-linked activities." (PMID 38732144, 2024). "Together with promoting metastasis, IRAK1 drives therapeutic resistance in different types of cancers." (PMID 39451208, 2024). "This activation was associated with an increased expression of inflammatory cytokines and subsequent enrichment of cancer stem cells (CSCs), all of which indicate that IRAK1 contributes to acquired resistance to paclitaxel treatment." (PMID 39451208, 2024). "Given the critical role IRAK1 plays in the activation of this pathway, research efforts have focused on its involvement in the progression of various cancer types." (PMID 39451208, 2024). "Another mechanism by which IRAK1 facilitates cancer cell migration and invasion is through the activation of MMPs, a family of endopeptidases that degrade proteins within the ECM." (PMID 39451208, 2024). "The selective inhibition or degradation of IRAK1 provides an avenue for safer and more effective interventions, especially in the context of cancer therapy." (PMID 38792088, 2024).
cancer (continued). "Many in vitro and in vivo studies have shown that inhibiting IRAK1 presents a promising strategy for the treatment and/or prevention of cancer metastasis and overcoming resistance." (PMID 39451208, 2024). "In our studies, we also tested this reported IRAK1/4 inhibitor but determined marginal anti-cancer activity towards EOC cell lines." (PMID 38796478, 2024). "Concomitantly with the promotion of metastasis, IRAK1 is also a main contributor to resistance to chemotherapies, targeted therapies, and radiotherapy in various types of cancer." (PMID 39451208, 2024). "At the same time, emerging support for IRAK1’s therapeutic links to cancers and inflammation with recent pre-clinical and clinical work make it an attractive target to pursue." (PMID 39543721, 2024). "Overall, numerous studies that utilize IRAK1 inhibitors, knockdown, or overexpression models have consistently highlighted the role of IRAK1 in the inhibition of cancer cell apoptosis and promotion of cell survival." (PMID 39451208, 2024). "The contribution of IRAK1 in angiogenesis has also been extensively studied in the context of wound healing and autoimmune diseases, outside of cancer." (PMID 39451208, 2024). "As examples, we experimentally validated three rare variants in cancer-associated genes (MFN2, FOSL2, and IRAK1), confirming their functional roles in regulating mRNA stability and cell proliferation." (PMID 38637555, 2024). "In a 2022 study, a comprehensive analysis was conducted to determine IRAK1 alterations across various types of cancer." (PMID 39451208, 2024). "Using SpectraView target evaluation, we prioritize IRAK1 serine-threonine kinase with emergent therapeutic links in inflammation and cancers." (PMID 39543721, 2024). "A co-culture study on lingual squamous cell carcinoma identified that IL-1β released by cancer cells leads to an upregulation of IL-1R and increased activation of IRAK-1 in CAFs." (PMID 39451208, 2024). "IRAK1 is converged upon by multiple oncogenic signaling axes and is increasingly recognized as a pivotal player in the complex process of cancer metastasis." (PMID 39451208, 2024). "Recent publications have summarized the role of IRAK1 in different types of cancers, while emphasizing its significance as a therapeutic target." (PMID 39451208, 2024). "This review aims to elucidate the mechanistic role of IRAK1 in cancer metastasis, with a focus on its involvement in mediating therapeutic resistance." (PMID 39451208, 2024). "This is a comprehensive review that summarizes the roles of IRAK1 in regulating metastasis-related signaling pathways of importance to cancer cell proliferation, cancer stem cells, and dissemination." (PMID 39451208, 2024). "The catalytic activity of IRAK1 has been reported to be important for cancer cell survival following exposure to radiotherapy or chemotherapy." (PMID 37370720, 2023). "This study shows that IRAK1 degrader have the potential to treat cancers dependent on the function of IRAK1 stents compared to IRAK1 inhibitors." (PMID 37261210, 2023). "The expression of miR-146a is altered in various cancers and reportedly targets IRAK1 and TRAF6, leading to the inactivation of the inflammatory, tumorigenic NF-kB signaling pathway, apoptosis stimulation, and cancer cell proliferation reduction." (PMID 37711209, 2023). "IRAK1 has been upregulated in many cancers and is considered as one possible target in cancer therapy." (PMID 37869102, 2023). "In conclusion, the high expression and the oncogenic role of IRAK1 in many of these cancers further justifies the need to investigate its role in PCa, as well as the therapeutic potential of targeting IRAK1 in PCa cells." (PMID 37370720, 2023). "However, low expression levels of IRAK1 may cause the failure of targeted cancer therapy." (PMID 37869102, 2023). "Additionally, IRAK1 mutation might reduce its role in cancer, requiring further exploration." (PMID 35669566, 2022).